CYP1B1-AS1 (CYP1B1 antisense RNA 1)
Synonyms: MGC34824; C2orf58
Gene: Long non-coding RNA gene on chromosome 2 (38,073,447 to 38,231,651, forward strand). Ensembl gene ENSG00000232973.
Gene Ontology:
Molecular function: U4 snRNA binding
Biological process: formation of quadruple SL/U4/U5/U6 snRNP; spliceosomal tri-snRNP complex assembly
Cellular component: U4/U6 x U5 tri-snRNP complex; U6 snRNP
Diseases named in the same sentence as CYP1B1-AS1 in open-access papers:
CYP1B1-AS1 is named in the same sentence as 1 disease in open-access papers, as found by Europe PMC text mining. Sharing a sentence is not in itself a finding about the gene and the disease.
CYP1B1-AS1 shares sentences with these, for which no sentence is quoted: breast carcinoma (1 paper).